MTSS1 (MTSS I-BAR domain containing 1)
Diseases named in the same sentence as MTSS1 in open-access papers (continued):
Sharing a sentence is not in itself a finding about the gene and the disease.
leukemia (3 papers, 2019 to 2021). A malignant (clonal) hematologic disorder, involving hematopoietic stem cells and characterized by the presence of primitive or atypical myeloid or lymphoid cells in the bone marrow and the blood. "For example, MTSS1, showing NKcell specific MAE, is a tumor suppressor gene in leukemia and plays an important role in the development of B cells." (PMID 34722498, 2021).
metastasis (3 papers, 2016 to 2020). The spread or migration of cancer cells from one part of the body (where they first appeared) to another. "Therefore, we believe that advanced lung metastasis after palliative surgery may correlate with upregulated MTSS1 expression." (PMID 27230279, 2016).
metastatic cancers (3 papers, 2013 to 2024). A carcinoma which has spread from the original site of growth to another anatomic site. "Metastasis Suppressor 1 (MTSS1), is inactivated in metastatic cancer and has prognostic value for breast cancer and lung cancer." (PMID 27935972, 2016). "The original findings of MTSS1 being absent or expressed at a low level in metastatic bladder carcinoma cell lines resulted in the dominant view that a lack of MTSS1 was a predictive factor for metastatic cancers." (PMID 39625546, 2024).
metastatic tumors (3 papers, 2013 to 2018). "Downregulation of MTSS1 has been observed in many types of human cancers, and complete loss of MTSS1 is associated with poorly differentiated metastatic tumors, and with poor survival rate." (PMID 24318128, 2013). "Finally, MDA-MB-231 cells treated with cmvIL-10 showed significant downregulation of metastasis suppressor 1 (MTSS1), a scaffolding protein that regulates cytoskeletal rearrangements and is frequently lost in metastatic tumors." (PMID 28228690, 2017).
triple-negative breast carcinoma (3 papers, 2021 to 2023). An invasive breast carcinoma which is negative for expression of estrogen receptor (ER), progesterone receptor (PR), and human epidermal growth factor receptor 2 (HER2). "For example, the metastasis suppressor genes CREB3L1 (cAMP-responsive element binding protein 3 like 1) and MTSS1 (metastasis suppressor 1) were recently found repressed in triple-negative breast cancer (TNBC)." (PMID 37369946, 2023). "MTSS1 expression levels are inversely correlated with the clinical pathology and prognosis in triple-negative breast cancer (TNBC) tissues." (PMID 37687058, 2023). "SCAMP1 dampens down the invasive ability of MTSS1 in triple-negative breast cancer cells through the trafficking mediated upregulation of RAC1-GTP, thus enhancing cell adhesion." (PMID 33493138, 2021). "The cooperative activity of MTSS1 and SCAMP1 prevents triple-negative breast cancer cell invasion whilst their silencing enhances the aggressiveness of these cancer cells." (PMID 33493138, 2021).
bladder urothelial carcinoma (2 papers, 2019 to 2020). "For example, DNMT3B-mediated methylation of the metastasis suppressor 1 (MTSS1) promoter epigenetically suppresses MTSS1 transcription in the urothelial carcinoma of the bladder." (PMID 33221743, 2020).
cardiomyopathy (2 papers, 2016 to 2024). A disease of the heart muscle or myocardium proper. "Some DEGs related to cytoskeleton organization (e.g. MTSS1, ACTN4 and CALD1), cardiomyopathy (e.g. ITGB5) and immune response (e.g. C1S and C1R), as well as some regulators (e.g. LEF1 and hsa-miR-33a) might play pivotal roles in the progression of DN." (PMID 27613243, 2016).
cervical carcinoma (2 papers, 2014 to 2016). A carcinoma arising from either the exocervical squamous epithelium or the endocervical glandular epithelium. "Another possible mechanism involves the potential association of MTSS1 expression in cervical cancer with hedgehog (Hh)-Gli signaling pathways." (PMID 25295101, 2014). "The results suggest that the dysregulation of MTSS1 may be involved in cervical carcinogenesis, and thus MTSS1 may be a novel diagnostic biomarker or therapeutic target in cervical cancer patients." (PMID 25295101, 2014). "MTSS1 may be a novel diagnostic biomarker or a therapeutic target in cervical cancer." (PMID 25295101, 2014). "This provides a basis for further investigation of the biological role of MTSS1 in the development and progression of cervical cancer." (PMID 25295101, 2014). "Elucidation of the specific mechanism of MTSS1 involvement in cervical cancer requires further studies using cervical cancer cell lines." (PMID 25295101, 2014). "When examining MTSS1 expression and clinicopathological factors, the strong positive MTSS1 expression rates in early-stage versus middle- and advanced-stage cervical cancer tissues were 39.13% and 82.35%, respectively." (PMID 25295101, 2014). "Cytoplasmic expression of MTSS1 was significantly greater in cervical carcinoma and CIN II–III tissues than in normal cervical tissues (χ2=40.000, P<0.01)." (PMID 25295101, 2014). "Within the cervical cancer group, early-stage cervical cancer tissues exhibited moderate to strong MTSS1 expression, and middle- and advanced-stage cervical cancer tissues exhibited strong positive MTSS1 expression." (PMID 25295101, 2014). "Among the 57 cases of cervical squamous carcinoma, the strong positive MTSS1 expression rate was significantly higher in middle- and advanced-stage cervical cancer specimens than in early stage cervical cancer specimens (χ2=42.043, P<0.05)." (PMID 25295101, 2014). "Furthermore, the strong positive expression of MTSS1 was significantly higher in middle- and advanced-stage cervical cancer than in early stage cancer (P<0.05)." (PMID 25295101, 2014). "However, cytoplasmic expression of MTSS1 was significantly higher in cervical carcinoma tissues when compared with normal cervical tissues (χ2=62.971, P<0.001)." (PMID 25295101, 2014). "The mechanism by which MTSS1 is involved in cervical cancer development remains unclear." (PMID 25295101, 2014). "In conclusion, in the present study, MTSS1 was found to be highly expressed in CIN II–III and cervical cancer tissues, and MTSS1 expression levels were positively correlated with the clinical stage of cervical cancer." (PMID 25295101, 2014). "In the present study, MTSS1 protein expression in CIN, cervical cancer and normal cervical tissues was examined by immunohistochemistry." (PMID 25295101, 2014). "MTSS1 expression was detected by immunohistochemistry in 147 cervical tissue specimens collected from 30 healthy individuals, 30 patients with cervical CIN I, 30 patients with CIN II–III and 57 patients with cervical cancer." (PMID 25295101, 2014). "The positive expression rate of MTSS1 was significantly higher in CIN II–III and cervical cancer tissues than in CIN I and normal cervical tissues (P<0.05), suggesting that MTSS1 may be important in cervical carcinogenesis." (PMID 25295101, 2014). "However, the expression and significance of MTSS1 have not been reported in precancerous cervical lesions or cervical cancer." (PMID 25295101, 2014).
glioblastoma (2 papers, 2016 to 2024). The most malignant astrocytic tumor (WHO grade IV). "For instance, the MTSS1 promotor region is heavily methylated in glioblastoma." (PMID 39625546, 2024). "Moreover, high levels of MTSS1, an actin-binding protein, inhibited migration in fibroblasts and in glioblastoma cells inhibited cell growth, colony formation, migration and invasion." (PMID 27206673, 2016).
liver cancer (2 papers, 2017 to 2023). An epithelial or non-epithelial malignant neoplasm that arises from the liver. "Fucoidan, a sulfated brown algal polysaccharide, suppresses EMT in liver cancer (HepG2) cells by upregulating miR-29b-3p to inhibit DNMT3B, a metastasis suppressor 1 (MTSS1) suppressor." (PMID 36835100, 2023).
medulloblastoma (2 papers, 2007 to 2021). A malignant, invasive embryonal neoplasm arising from the cerebellum. "Given the prime importance of this pathway for cerebellar development and tumorigenesis, we assessed expression of Mtss1 in the developing murine cerebellum and human medulloblastoma specimens." (PMID 17925019, 2007).
nasopharyngeal carcinoma (2 papers, 2023 to 2024). A carcinoma arising from the nasopharyngeal epithelium. "For instance, MTSS1 suppresses the migration and invasion of nasopharyngeal carcinoma cells in vitro by facilitating cytoskeletal remodeling at cell–cell junctions and promoting the assembly of E-cadherin, β-catenin, and F-actin in adherens junctions." (PMID 39625546, 2024). "MTSS1 was shown to suppress nasopharyngeal carcinoma (NPC) cell migration and invasion in vitro through cytoskeletal remodeling at cell–cell borders and the assembly of E-cadherin/β-catenin in adherens complexes." (PMID 39625546, 2024).
serous ovarian carcinoma (2 papers, 2021 to 2024). "In high‐grade serous ovarian carcinoma (HG‐SOC), high expression of miR‐182 promotes tumorigenesis by targeting Breast Cancer Gene 1 (BRCA1), High Mobility Group AT‐Hook 2 (HMGA2), and Metastasis Suppressor 1 (MTSS1) genes." (PMID 39617640, 2024).
acute promyelocytic leukemia (1 paper, 2023). An aggressive form of acute myeloid leukemia (AML), characterized by arrest of leukocyte differentiation at the promyelocyte stage, due to a specific chromosomal translocation t(15;17) in myeloid cells. "Moreover, treatment of acute promyelocytic leukemia cells with all-trans retinoic acid, which is included in the curative treatment regime, could increase MTSS1 mRNA levels." (PMID 37920825, 2023).
brain glioma (1 paper, 2020). A malignant glioma that involves the brain. "Correlation analysis of the expression levels of miR-182 and MTSS1 in brain gliomas showed that miR-182 expression was negatively correlated with MTSS1 expression (P < 0.0001), suggesting that overexpression of miR-182 might affect the regulation of MTSS1 expression." (PMID 32913477, 2020).
cholangiocarcinoma (1 paper, 2022). A carcinoma that arises from the intrahepatic biliary tree (intrahepatic cholangiocarcinoma) or from the junction, or adjacent to the junction, of the right and left hepatic ducts (hilar cholangiocarcinoma). "MiR-96 was upregulated in cholangiocarcinoma and positively associated with poor prognosis; its upregulation may promote cholangiocarcinoma cell proliferation, migration and invasion by targeting MTSS1." (PMID 35768865, 2022).
chronic hepatitis B infection (1 paper, 2016). "Therefore, there is a possibility that the virus infection plays some role in the expression of MTSS1, which needs further study to identify the role of chronic hepatitis B infection in MTSS1 regulation in HCC." (PMID 27230279, 2016). "In our study, patients had chronic hepatitis B infection which progressed to HCC, and we found that the poor prognosis of hepatitis B-related HCC patients following palliative hepatectomy associates with elevated MTSS1 mRNA expression." (PMID 27230279, 2016).
gastric tumors (1 paper, 2010). "Loss of MTSS1 expression occurred more frequently in large gastric tumors (invasion to level T3-T4) (76.1%) than in small ones (level T0-T2) (55.4%; P < 0.001) and more frequently in gastric tumors with regional LN metastasis (76.3%) than in N0-stage tumors (57.6%; P < 0.001)." (PMID 20712855, 2010).
hepatitis B (1 paper, 2016). "We investigated the MTSS1 mRNA expression in residual tumor and analyzed its association with prognosis in patients with hepatitis B-related HCC after palliative resection." (PMID 27230279, 2016). "The poor prognosis of hepatitis B-related HCC patients following palliative hepatectomy associates with elevated MTSS1 mRNA expression; therefore, MTSS1 may provide a new research field for HCC diagnosis and treatment." (PMID 27230279, 2016). "Patients with hepatitis B-related HCC exhibiting high MTSS1 mRNA levels in the residual tumor show poor prognosis after hepatectomy." (PMID 27230279, 2016).
Lewis lung carcinoma (1 paper, 2023). "We further ectopically expressed Mtss1 in Lewis lung carcinoma (LLC) cells and analyzed xenograft tumorigenesis by subcutaneous inoculation of the cells in mice." (PMID 36810288, 2023).
myeloid neoplasm (1 paper, 2015). Proliferation of myeloid cells originating from a primitive stem cell. "However, whether MTSS1 plays a role in the pathogenesis of myeloid neoplasms and how MTSS1 expression and MTSS1-mediated signaling are altered in the context of specific hematopoietic oncogenes remains unclear." (PMID 25996952, 2015).
oesophageal cancer (1 paper, 2011). "Over-expression of MTSS1 also significantly inhibited the motile nature of oesophageal cancer cells." (PMID 21696600, 2011). "KYSE510-MTSS1-Rib oesophageal cancer cells were significantly more invasive than the control cells which expressed MTSS1 (p < 0.0001)." (PMID 21696600, 2011). "Here, we sought to determine MTSS1 expression in oesophageal cancer patient specimens and evaluate the clinical implications of MTSS1 expression in oesophageal squamous cell carcinoma." (PMID 21696600, 2011). "In the present study, the expression levels of MTSS1 were examined in several oesophageal cancer cell lines with different aggressiveness (from well or moderate to poorly differentiated)." (PMID 21696600, 2011). "A panel of oesophageal cancer cell lines was examined for the presence of MTSS1 through RT-PCR." (PMID 21696600, 2011). "Using over-expression and knockdown approach, we created sublines from ESCC cells and further demonstrated that MTSS1 expression in ESCC cells significantly influenced the aggressiveness of the oesophageal cancer cells, by reducing their cellular migration and in vitro invasiveness." (PMID 21696600, 2011). "Finally, the presence of MTSS1 has also been shown to affect oesophageal cancer cells invasion." (PMID 21696600, 2011).
oral cancer (1 paper, 2023). "MiR-182-5p directly targeted MTSS1, and by down-regulating MTSS1 expression levels it may promote invasion and migration in oral cancer." (PMID 37635248, 2023).
osteosarcoma (1 paper, 2021). A usually aggressive malignant bone-forming mesenchymal neoplasm, predominantly affecting adolescents and young adults. "Subsequently, researchers observed that the overexpression of miR-411 stimulates both osteosarcoma cell migration and proliferation via reducing the expression of metastasis suppressor protein 1 (MTSS1)." (PMID 35011442, 2021).
pancreatic cancer (1 paper, 2017). "Moreover, MTSS1 was a gene from our list that had been previously linked to metastatic progression in a number of different cancer models, but that had yet to be investigated in pancreatic cancer." (PMID 28146435, 2017). "If the inflammatory stromal microenvironment is responsible for upregulation of COX-2 in the pancreatic cancer cells, then it may also be responsible for the upregulation of the SCFβTRCP proteasome, which leads to increased degradation and loss of MTSS1 expression." (PMID 28146435, 2017). "In order to functionally determine the role MTSS1 plays in pancreatic cancer aggressiveness, we first showed that MTSS1 knockdown significantly increases PDAC cell migration and invasion." (PMID 28146435, 2017). "In this study, we show that MTSS1 plays an important role in suppressing pancreatic cancer cell invasion and migration driven by the tumor microenvironment." (PMID 28146435, 2017). "In order to determine if MTSS1 expression correlated with metastatic potential, we determined the level of MTSS1 expression in six human pancreatic cancer cell lines that were originally derived from either primary or metastatic lesions." (PMID 28146435, 2017).
pancreatic ductal adenocarcinoma (1 paper, 2021). An infiltrating adenocarcinoma that arises from the epithelial cells of the pancreas. "Interestingly, PTEN has been shown to interact with the metastasis suppressor protein 1 (MTSS1), the loss of which has been shown to result in a significant increase in cellular migration and invasion in pancreatic ductal adenocarcinoma cells." (PMID 34943931, 2021).
papillary carcinoma (1 paper, 2014). A malignant epithelial neoplasm characterized by a papillary growth pattern. "Serous papillary carcinomas were most frequent in this series and this type of histology showed borderline association with expression of MTSS1 (p = 0.092)." (PMID 24961659, 2014).
periodontitis (1 paper, 2015). An acute or chronic inflammatory process that affects the tissues that surround and support the teeth. "CD24, EST1, MTSS1, ING3, CCND2 and SYNE2 may have the potential to be used as targets for periodontitis diagnosis and treatment.; however, more research is still needed to validate our findings." (PMID 26705104, 2015). "EST1, MTSS1, ING3, CCND2 and SYNE2, as well as their corresponding miRNAs, might be potential therapeutic targets for periodontitis." (PMID 26705104, 2015).
squamous carcinoma (1 paper, 2024). "Interestingly, MTSS1 was described to localize at junctions in kidney epithelium and squamous carcinoma cells through an I-BAR domain, and to be essential for maintenance of cell–cell adhesion by promoting Rac1 activation." (PMID 39404373, 2024).